TNF (tumor necrosis factor)
Diseases named in the same sentence as TNF in open-access papers (continued):
Sharing a sentence is not in itself a finding about the gene and the disease.
tumor (continued). "As monotherapy, rHER2 ECD mRNA-LNPs induced high anti-HER2 antibody titers, polyfunctional CD8+ T cells (IFNγ+/TNFα+), and durable memory T cells, achieving 87.0% tumor inhibition." (PMID 41993212, 2026). "Thermal triggers tumor cell expression of HSP70/90, boosts antigen presentation efficiency, and stimulates IL‐6 and TNF‐α secretion to activate innate immunity and enhance immune recognition of tumor cells." (PMID 41298282, 2026). "Our analysis reveals a dual role of T cell-macrophage crosstalk: CD4+ and CD8+ exhausted T cells drive anti-tumor M1-like TAMs activation via TNF-TNFRSF1A, TNFSF14-LTBR, and ICAM1-ITGAL/ITGB2." (PMID 42001468, 2026). "NK cells do this through direct lysis of CSCs or by releasing cytokines like interferon-gamma (IFN-γ) and tumor necrosis factor-alpha (TNF-α), which inhibit tumor growth and metastasis by driving differentiation of CSCs." (PMID 41898674, 2026). "First, the in ovo activation of CAR-T cells and their functionality in the tumor were investigated through the intra-tumoral gene expression of human IFNγ and human TNFα by RT-qPCR at EDD18." (PMID 41596451, 2026). "Genomic findings were interpreted in the context of TNF α pathway biology and tumor microenvironment interactions relevant to GBM progression." (PMID 42130630, 2026). "These probiotics, once administered to the host, can target the tumor site and release TNF-α, promoting the destruction of cancer cells." (PMID 41355950, 2026). "NK cells, as innate immune cells, play a significant role in anti‐tumor immunity through mechanisms such as the perforin/granzyme pathway, the Fas‐FasL and TNF‐α‐TNFR‐1 pathways, and antibody‐dependent cell‐mediated cytotoxicity." (PMID 41560416, 2026). "For example, IL-6 and TNF-α have been shown to protect tumor cells from the cytotoxic effects of chemotherapy and radiation by activating survival pathways such as AKT and MAPK." (PMID 41497141, 2026). "By contrast, 3D-primed ADSCs preserved organoid structure but markedly enhanced tumor cell migration through soluble factors, accompanied by increased IL-6 and TNF-α and reduced IL-10 secretion during co-culture." (PMID 41681933, 2026). "Inflammatory factors and damage-associated molecular patterns(DAMPs) activate this pathway, increasing expression of TNF-α, IL-6, and other pro-inflammatory mediators to amplify inflammation and sustain a tumor-promoting environment." (PMID 41601649, 2026). "In this study, we present a strategy to uncouple tumor necrosis factor (TNF)-like cell death induction from TNFR2 agonism in a tumor-targeted fashion." (PMID 41952996, 2026). "This dual role creates a conundrum in which TNF can be either beneficial or detrimental for a tumor, depending on the context." (PMID 41651411, 2026). "This has allowed the engineering of probiotics such as Lactobacillus strains, which have been modified to produce therapeutic proteins like tumor necrosis factor-alpha (TNF-α), a cytokine that can enhance immune responses and promote tumor cell death." (PMID 41355950, 2026). "TNF-α, initially identified for its tumor necrosis-inducing properties, can trigger apoptotic pathways in tumor cells and activate cytotoxic immune responses, especially in early disease stages or acute inflammatory settings." (PMID 41497141, 2026). "Our findings support this concept, suggesting that rBCG amplifies neutrophil-dependent dendritic cell activation, resulting in higher TNF-α production in the spleen and enhanced NK cell activation at the tumor site." (PMID 41522339, 2026). "For example, one can envision combining optogenetic stimulation of the vagus nerve or LC—aimed at reducing systemic immunosuppression by lowering IL‐6 and TNF—with checkpoint inhibitors or tumor vaccines to convert “cold” tumors into “hot” ones." (PMID 41583906, 2026).
tumor (continued). "BALF data obtained during routine clinical care were retrospectively collected for tumor markers (CEA, CYFRA21-1, NSE, ProGRP), cytokines (IL-6, IL-8, TNF-α, IL-10), ctDNA mutation profiles, and immune-cell subpopulations." (PMID 41970393, 2026). "The tumor necrosis factor (TNF) ligand, which is generated by stromal cells, tumor-associated macrophages, endothelial cells, and cancer cells, has anti-tumor effects and amplifies the action of CD8+ and CD4+ T cells, inducing apoptosis and inflammation." (PMID 41596472, 2026). "Consistent with these cellular changes, elevated levels of IFN-γ and TNF-α were detected in the tumour tissues of ICC@G-PL-treated mice." (PMID 41510149, 2026). "Tumor necrosis factor alpha (TNF-α) is a pleiotropic cytokine that can both facilitate tumor progression and directly mediate tumor cell killing." (PMID 41651411, 2026). "M1 cells are characterized by a pro-inflammatory phenotype; they express CD80, CD86, CD40, and inducible nitric oxide synthase (iNOS), produce pro-inflammatory cytokines (IL-1β, TNFα), and provide anti-infective and anti-tumor activity." (PMID 41596489, 2026). "Tumor necrosis factor-α (TNF-α) exhibits a dual role in the tumor microenvironment: at high concentrations, it induces cell death and exerts anti-tumor effects, while at low doses, it demonstrates pro-tumorigenic activity." (PMID 41956989, 2026). "In tumor-bearing mice, antitumor efficacy, serum cytokines (TNF-α, IFN-γ, IL-6, IL-2, IL-10), and hematological indices were evaluated." (PMID 41965546, 2026). "Tumor necrosis factor receptor 2 converts the tumor inhibiting ability of TNF-α into a tumor advocating factor, thereby directly promoting the proliferation of some types of cancers such as lung, breast, and colon cancer." (PMID 40343927, 2025). "NK cells are also capable of modulating the immune response by producing cytokines, especially IFN-γ and TNF, two potent inflammatory cytokines that activate macrophages and lymphocytes at the site of infection or tumor environment." (PMID 40299429, 2025). "Strikingly, A1R but not A3R CAR T cells produced significantly higher levels of both IFNγ and TNF when cocultured with either tumor cell line." (PMID 40610421, 2025). "Pro-inflammatory cytokines, such as TNF-α, IL-6, and IL-11, mediate the tumor-promoting function of M2 macrophages in cancer cells by activating the NF-κB/STAT3 pathways." (PMID 40422244, 2025). "Increased NOS2-derived NO promotes metastasis, where higher clustering of NOS2+ tumor cells leads to increased oncogenic pathway signaling and immune-modulatory proteins, including IL-1, IL-6, IL-8, and TNF-α." (PMID 40663402, 2025). "Previous work from our group demonstrated that macrophages when exposed to a pro-inflammatory environment such as TNF-α, adopt a pro-tumoral phenotype that supports tumor progression." (PMID 40567500, 2025). "The uniform manifold approximation and projection (UMAP) diagram revealed that BAX, IL1B, and TNF were predominantly expressed in epithelial cells and macrophages in tumor tissues." (PMID 39744500, 2025). "Leronlimab reduced circulating tumor-associated cells and modulated CCR5-related cytokine production (CCL5, IL-6, and TNF-α), highlighting the potential of CCR5 blockade to reprogram the immunosuppressive microenvironment." (PMID 40868199, 2025). "In lymphocytes, upregulation of TNF gene expression can be mediated by T-cell activation, which regulates the immune response of tumor cells." (PMID 39744500, 2025). "M1 macrophages, known for their anti-tumoral and pro-inflammatory functions, release cytokines like TNF-alpha and IL-2, promoting immune responses against the tumor." (PMID 40330466, 2025). "Many studies have demonstrated that medicinal plants can inhibit cancer cell generation by reducing the increased expression of NF-κB and TNF-α, thus reducing tumor volume and weight as well as tumor burden and incidence." (PMID 40002867, 2025).
tumor (continued). "Tumor-infiltrating lymphocytes produce a range of cytokines, including IFN-γ and TNF-α, which inhibit tumor growth and promote tumor cell apoptosis." (PMID 40521361, 2025). "Many of them can act as factors enhancing tumor progression, activating angiogenesis (IL-1ß, TNF-α), tumor cell migration (IL-1ß, IL-6, IL-8), epithelial cell metaplasia (IL-6), and some stimulators and products of T regs (IL-10)." (PMID 40806737, 2025). "Differentiation by sNK cells was inhibited less by the antibodies to IFN-γ and TNF-α when compared to that mediated by the primary activated NK cells, suggesting the role of other unexplored mechanisms in sNK cell-induced tumor differentiation." (PMID 40890122, 2025). "TNF‐α, primarily produced by macrophages, exhibits dual roles in cancer, promoting tumor progression via angiogenesis and invasion while also exerting anti‐tumor effects through immune activation." (PMID 40922069, 2025). "PI3K-Akt signaling pathway and TNF signaling pathway, both crucial for inflammation and cancer cell survival, were downregulated, further impairing tumor progression." (PMID 41411347, 2025). "Pro-inflammatory mediators in the tumor microenvironment, such as TNF-α, can promote cancer cell proliferation, angiogenesis, and metastasis, thereby facilitating tumor growth." (PMID 40430470, 2025). "For example, TLR agonists (e.g., CpG ODNs) can stimulate macrophages to release proinflammatory cytokines (including TNF-α and IL-12), thereby enhancing the immunological attack within the tumor microenvironment." (PMID 41002423, 2025). "Inflammatory factors such as IFN-γ, TNF-α, IL-6, and IL-12 have been shown to enhance the body’s anti-tumor response." (PMID 41383334, 2025). "Excess white adipose tissue contributes to elevated levels of circulating free fatty acids and adipokines such as leptin, IL-6, and TNF-α, promoting a chronic inflammatory state that supports tumor progression." (PMID 40895542, 2025). "TGFβ has been reported to promote EMT in tumor cells, while TNFα, IL-6, and IL-1 can also promote tumor ETM by upregulating gene expression related to transcription factors such as NF-κB and STAT3." (PMID 39981173, 2025). "Consistent with observations in the murine system, overexpression of hA1R on human anti-Lewis Y CAR T cells enhanced the production of IFNγ and TNF by CAR T cells upon coculture with either OVCAR-3 or MCF7 (both Lewis Y+) tumor cells." (PMID 40610421, 2025). "Simultaneously, their secretion of TNF-α and IL-10 promotes regulatory T (Treg) cell-mediated immune tolerance, weakening anti-tumor immune responses and enhancing tumor progression." (PMID 40299416, 2025). "Tub A, a selective HDAC6 antagonist, exhibits low neurotoxicity and multimodal efficiency: it suppresses pro-inflammatory cytokines (TNF-α and IL-6), restores tumor-suppressive primary cilia, and inhibits viral RNA synthesis." (PMID 41135681, 2025). "System-level analyses have cautioned that alterations in the TNF axis can influence drug exposure and tumor cell apoptosis." (PMID 41584509, 2025). "Therapeutic strategies focus on enhancing the immune-activating properties of IL-2, IL-7, IL-12, and IL-15, while also suppressing the pro-inflammatory and tumor-promoting cytokines, such as TNF-α, IL-1β, and IL-6." (PMID 40508202, 2025). "TNF-α’s involvement in promoting tumorigenesis and its complex role in the tumor microenvironment highlight its potential as both a therapeutic target and a challenge for effective treatment." (PMID 40558596, 2025). "ILC3s play a multifaceted role in cancer immunity, with anti-tumor effects primarily driven by their ability to recruit and activate effector cells, produce cytokines like IL-22 and TNF, form TLS, and present antigens." (PMID 40963622, 2025). "The Nrf-2 factor is responsible for the protective antiapoptotic effect of A2780 tumor cells, and TNF-α, on the contrary, induces the apoptosis of A2780 tumor cells." (PMID 41226774, 2025).
tumor (continued). "While N1 neutrophils exert cytotoxic activity through ROS, TNF-α, and direct tumor cell killing, N2 neutrophils promote angiogenesis, extracellular matrix remodeling, and immunosuppression, thereby facilitating metastatic dissemination." (PMID 41394845, 2025). "Under conditions of chronic inflammation, TNF-α supports tumor development and proliferation through multiple mechanisms." (PMID 41376630, 2025). "No such differences in cytokine levels were evident in the draining lymph nodes, suggesting that the increase of IFN-γ and TNF-α in the LLC tumor bed in the presence of CD8+ T cells is a localized phenomenon." (PMID 40553564, 2025). "TNF-α is involved in all stages of tumor development, from the initial transformation of cells to metastasis." (PMID 39941912, 2025). "Once activated, they subsequently also secrete pro-inflammatory cytokines such as TNF-α, IL-1β, IL-6, IL-8, IL-12, and IL-23, which work together to suppress tumor growth." (PMID 40427130, 2025). "Cytotoxic CD8+ T cells (CTLs) bind to MHC I and secrete cytokines such as granzyme B, perforin, IFN-γ, and TNF-α as well as mediate tumor cell apoptosis through FasL/Fas interaction." (PMID 40458394, 2025). "We also found significantly increased levels of intratumoral cytokines IFN-γ, TNF-α, and IL-5, known to be T helper 1 (Th1) and T helper 2 (Th2)-related cytokines that play a role in anti-tumor immune responses." (PMID 39743545, 2025). "Tumor necrosis factor-alpha is an inflammatory cytokine that has been established to actively induce inflammation in cancer, thereby promoting tumor formation." (PMID 40008130, 2025). "To further understand the potential interactions between immune cells, we also performed an analysis of cytokine expression genes in tumours; the most expressed cytokines were TGFβ, IL-18, IL-15, and TNFα." (PMID 41301032, 2025). "M1 macrophages are typically associated with anti-tumor activities, producing pro-inflammatory cytokines like TNF-α and IL-12, and promoting tumor cell killing." (PMID 41164132, 2025). "On the contrary, M1 macrophages express CD86 and iNOS, exerting tumor-suppressive effects by producing IL-1α/β, IL-6, TNF-α, and ROS." (PMID 41035634, 2025). "Tumor cells and inflammatory cytokines such as TNF-α and IL-1 stimulate BMECs to produce higher amounts of NO via the upregulation of inducible nitric oxide synthase (iNOS)." (PMID 40806429, 2025). "Gudgeon and colleagues found that the uptake of tumor-associated succinate significantly inhibited T cell degranulation, interferon-γ (IFN-γ) expression, and Tumor Necrosis Factor-α (TNF-α) expression, resulting in impaired effector functions of T cells." (PMID 39781339, 2025). "M1-type macrophages are induced by Th1 cytokines and are responsible for the presentation of tumor-specific antigens and the release of pro-inflammatory cytokines (e.g., IL-1, IL-6, and TNF-α) to augment the anti-tumor immune response." (PMID 39975599, 2025). "The activated T lymphocytes secrete a large amount of TNF‐α, which binds to receptors on the surfaces of tumor cells to activate the Caspase signaling pathway, further enhancing the activity and expression of Caspase‐3." (PMID 40497373, 2025). "TAMs can produce different interleukins and factors, such as IL-6, IL-12, and TNF-α, through NF-κB-mediated signaling to induce the apoptosis of tumor cells." (PMID 41029711, 2025). "TNF-α, a small-molecule protein secreted by macrophages, is one of the bioactive factors with the strongest direct tumor-killing effect." (PMID 41440918, 2025). "Next, to assess the effect of IFN-γ + TNF-α in a 3D tumor model such as BC spheroids and the effect of the cytokines on the susceptibility of spheroids to NK cell-mediated killing, MCF-7, MDA-MB-231 and MDA-MB-468 cells were cultured in low-adherent plates." (PMID 41102150, 2025).
tumor (continued). "For example, IL-6 activates the JAK/STAT3 axis to promote tumor growth and immune evasion, while TNF-α and IL-8 enhance tumor invasion via NF-κB and MAPK signaling." (PMID 41502517, 2025). "By analysing IL1β, IL10, IL18, TNF-α, TLR4, GATA3, and CD68 expression in 50% of PCa HHV-infected FFPE with an elevated inflammation index (61.8%/21), we detected hyper-expressed levels of IL1β, IL18, and TNF-α in the tumour microenvironment." (PMID 40430084, 2025). "TNF-α can support tumour growth but also induces neutrophil apoptosis, implying transient antitumour potential." (PMID 41451221, 2025). "As primary antitumor effectors, CD8+ CTLs eliminate tumor cells via perforin/granzyme-induced membrane disruption, Fas/FasL-mediated apoptosis, and TNF/TNFR signaling amplification." (PMID 40510347, 2025). "A pathway analysis of the tumor cells revealed that co-culture upregulated multiple pathways, including epithelial-to-mesenchymal transition, tumor necrosis factor alpha signaling and inflammatory response, and downregulated cell cycle pathways." (PMID 40229600, 2025). "TNF-α, produced by macrophages, promotes epithelial-mesenchymal transition, aiding metastasis; high TNF-α expression predicts tumor deterioration." (PMID 40297577, 2025). "Further studies have shown that TAMs induce PD-L1 expression in gastric cancer cells through IL-6 and TNF-α signaling, thereby helping tumor cells evade cytotoxic T cell killing." (PMID 41041337, 2025). "In GC, TNF drives tumor progression through NF-κB and MAPK pathways, promotes angiogenesis, cell proliferation and metastasis, and suppresses antitumor immunity." (PMID 41376630, 2025). "These TAMs showed elevated TNF-α and reduced IL-4 secretion, contributing to stronger anti-tumor immunity." (PMID 40427130, 2025). "Mainly, IL-6 and IL-1β are produced by infiltrated mononuclear cells, stimulating the release of TNF and angiogenic factors such as VEGF, which are implicated in tumour initiation and progression." (PMID 41440367, 2025). "TNF‐α is a systemic inflammatory cytokine that plays a role in the cytotoxic activity of other cytokines against tumor cells." (PMID 40620232, 2025). "The Th1 subtype of CD4+ T cells (Th cells) can produce interferon gamma (IFNγ) and TNF-α to directly kill cancer cells and can exert anti-tumor effects by aiding B cells and CD8+ cells." (PMID 41001032, 2025). "These microbes promote the secretion of pro-inflammatory cytokines (such as IL-6, TGF-β, and TNF-α) by CAFs, which enhances tumor cell proliferation and drives tumor growth and metastasis." (PMID 41473772, 2025). "In this hypoxic state, macrophages are also oxygen-deprived, and HIF-1α stimulates tumor-associated macrophages (TAMs) to produce various factors, such as VEGF, IL-1β, TGF-β1, tumor necrosis factor (TNF)-α, basic fibroblast growth factor (bFGF), and IL-10." (PMID 40034694, 2025). "Three pathways closely related to tumor development were selected from these eight pathways as hub pathways for MGFD in the treatment of PCa: TNF signaling pathway (hsa04668), cellular senescence (hsa04218), and FoxO signaling pathway (hsa04068)." (PMID 41011149, 2025). "CD8+ T cells (cytotoxic T lymphocytes) release IFN-γ and TNF-α, promoting tumor cell killing, but can become exhausted in nutrient-poor, hypoxic conditions." (PMID 40297580, 2025). "The resected tumor mass from the G2 group showed an elevated IFN-γ level and reduced TNF-α and IL-6 levels; this finding suggested the infiltration of activated T cells into the tumor tissues." (PMID 40539041, 2025).